AHR (aryl hydrocarbon receptor)
Diseases named in the same sentence as AHR in open-access papers (continued):
Sharing a sentence is not in itself a finding about the gene and the disease.
E. coli infections (2 papers, 2016 to 2022). "Previous studies also indicated that mice with AhR deficiency had higher susceptibility to Citrobacter rodentium (C. rodentium), which is a model that mimics human E. coli infections." (PMID 35727038, 2022). "E. coli infection is one of the main causes of endometritis, and E. coli or LPS can activate AhR signaling that regulates the host inflammatory response and barrier integrity." (PMID 35727038, 2022).
endometritis (2 papers, 2022 to 2025). An acute or chronic, usually bacterial infectious process affecting the endometrium. "Altogether, our study identified that gut-dysbiotic mice had increased severity of endometritis, which was associated with impaired AhR activation." (PMID 35727038, 2022). "To investigate whether AhR activation was associated with E. coli-induced endometritis, we measured the protein expression of AhR in uterine tissues from control and E.coli-induced endometritis mice." (PMID 35727038, 2022). "AhR activation accounts for mucosal inflammation limitation and barrier function maintenance, which are associated with the immunopathology of endometritis." (PMID 35727038, 2022). "The purpose of this study is to assess the effects and underlying mechanism of AhR activation and gut microbiota-mediated dietary tryptophan (Trp) metabolism on infection-induced inflammation using an Escherichia coli (E. coli)-induced endometritis model in mice." (PMID 35727038, 2022). "Its mechanism is to activate AhR and inhibit the NF-κB signaling pathway, which leads to the inhibition of inflammatory cytokines and alleviates endometritis, thereby achieving therapeutic effects." (PMID 41141592, 2025). "E. coli-induced endometritis was rescued by pharmacological activation of AhR, dietary Trp intervention, and supplementation with AhR ligands and producer." (PMID 35727038, 2022). "To study the role of AhR activation in E. coli-induced endometritis immunopathology, we pharmacologically regulated the AhR signaling pathway using Ficz or CH223191." (PMID 35727038, 2022). "Gut dysbiosis impairs uterine AhR activation, reduces intestinal AhR producer abundance, and aggravates E. coli-induced endometritis in mice." (PMID 35727038, 2022). "Further studies should investigate other potential mechanisms by which L. reuteri activates AhR to improve endometritis or other diseases and the possibility of a combined treatment of Trp and L. reuteri to improve endometritis." (PMID 35727038, 2022). "Gut dysbiosis impaired AhR activation, which resulted in an E.coli-induced increase in endometritis score." (PMID 35727038, 2022). "Gut dysbiosis reduced the abundance of AhR ligand producers including Lactobacillus spp., damaged AhR activation, and exacerbated E. coli-induced endometritis." (PMID 35727038, 2022). "We found that AhR activation improved E. coli-induced endometritis by limiting inflammation expansion and restoring epithelial barrier functions." (PMID 35727038, 2022). "Abrogation of the gut microbiota by ABX weakened AhR activation in the uterus, induced uterine inflammation, and aggravated E. coli-induced endometritis." (PMID 35727038, 2022). "To confirm the role of AhR activation in the Ficz-mediated protective effects on E. coli-induced endometritis, we detected the activation of the uterine AhR pathway by Western blotting." (PMID 35727038, 2022). "To study the effects of AhR activation on endometritis, we pretreated mice with Ficz, an AhR agonist, followed by E. coli stimulation." (PMID 35727038, 2022). "Taken together, these results demonstrate that gut microbiota disruption impairs AhR activation and facilitates E. coli-induced endometritis in mice." (PMID 35727038, 2022). "Collectively, these results suggest that AhR activation alleviates E. coli-induced endometritis by affecting barrier function and inflammatory signal transduction." (PMID 35727038, 2022). "The protective role of I3A on LPS-induced endometritis was reversed by AhR inhibitor CH223191." (PMID 41141592, 2025). "L. reuteri consumption alleviates E. coli-induced endometritis in mice in an AhR-dependent manner." (PMID 35727038, 2022). "The present study demonstrated that activating AhR alleviated E.coli-induced endometritis in mice." (PMID 35727038, 2022).
endometritis (continued). "Our results suggest an important role of microbiota-mediated AhR activation in the pathogenesis of endometritis and provide potential strategies for the intervention of infectious diseases and reproductive health by regulating the gut microbiota and metabolism." (PMID 35727038, 2022). "AhR activation ameliorates E. coli-induced endometritis in mice." (PMID 35727038, 2022). "To examine whether the protective effects of L. reuteri on E. coli-induced endometritis depended on the activation of AhR, we blocked AhR by treating mice with CH223191 after each oral gavage of L. reuteri for 3 weeks." (PMID 35727038, 2022). "Moreover, supplementation with a diet enriched in high Trp ameliorated E. coli-induced endometritis by increasing ligand levels of AhR." (PMID 35727038, 2022). "Whether and how gut microbiota-mediated AhR activation regulates the pathogenesis of pathogen-induced endometritis remains unknown." (PMID 35727038, 2022). "Inhibition of the AhR pathway aggravates E. coli-induced endometritis in mice." (PMID 35727038, 2022). "Similar to our previous study, aggravated inflammatory status was also observed in ABX-pretreated mice followed by E. coli stimulation, which suggests that impairment of AhR activation in the uterus by the gut microbiota alteration facilitates the progression of E. coli-induced endometritis." (PMID 35727038, 2022). "To further confirm whether the AhR pathway was required for host defense against E. coli-induced endometritis, we blocked AhR activation by pretreating mice with the specific AhR inhibitor CH223191 before Ficz and E. coli administration." (PMID 35727038, 2022). "Given that Lactobacillus was enriched in control mice but depleted in gut-dysbiotic mice, and previous findings that L. reuteri activated AhR through metabolizing Trp and affected disease outcomes, we investigated the impact of L. reuteri consumption on E.coli-induced endometritis." (PMID 35727038, 2022). "Here, we tested whether gut microbiota-regulated AhR activation by Trp metabolites suppressed infection-induced inflammation using a mouse endometritis model." (PMID 35727038, 2022). "Notably, higher AhR level was detected in the E.coli treatment group than the control group, which suggests that the AhR pathway participates in the pathogenesis of E. coli-induced endometritis." (PMID 35727038, 2022). "AhR participates in the physiological activity of the uterus, and E. coli is one of the main pathogens of endometritis, which indicates that the AhR signaling pathway may play an important role in the pathogenesis of E. coli-induced endometritis." (PMID 35727038, 2022). "The current study found that AhR activation ameliorated E. coli-induced endometritis, and inhibition of AhR produced negative results." (PMID 35727038, 2022).
enteropathy (2 papers, 2019 to 2024). "As a matter of fact, the beneficial effects of AhR restoration in improving gliadin-induced enteropathy upon specific probiotic treatment or dietary approaches has been already shown." (PMID 38719750, 2024).
Erythema (2 papers, 2018 to 2022). Redness of the skin, caused by hyperemia of the capillaries in the lower layers of the skin. "Compound actuation of erythema, epidermal thickening, and tissue cytokine levels was reduced by topical treatment of AhR-sufficient mice with Tapinarof in a mouse model of AhR." (PMID 35625824, 2022). "Next, we exposed HaCaT KC to 50 J/m2 and 200 J/m2 UVB (approximately equivalent to 0.25 and 1 minimal erythema dose for a fair-skinned individual) and subsequently treated the cells with the AHR antagonist 3′-methoxy-4′-nitroflavone (MNF, 20 μM) to exclude putative UV-filtering effects." (PMID 30013037, 2018).
extramammary Paget disease (2 papers, 2019 to 2022). A malignant neoplasm in which there is infiltration of the skin by neoplastic large cells with abundant pale cytoplasm and large nuclei with prominent nucleoli (Paget cells). "Several reports have suggested possible links between the AHR system and tumor biology in Merkel cell carcinoma (MCC) and extramammary Paget's disease (EMPD)." (PMID 31552251, 2019).
Glucose Metabolism Disorders (2 papers, 2024 to 2025). "A comprehensive literature search since 2014 was conducted using PubMed and Web of Science to identify studies involving AhR in drug-induced glucose metabolism disorders." (PMID 41440753, 2025).
gout (2 papers, 2018 to 2024). A condition characterized by painful swelling of the joints, which is caused by deposition of urate crystals. "Probenecid, a drug that reduces uric acid levels and is used to treat gout, was employed to elevate uremic metabolites levels as done previously, with the goal of increasing muscle AHR activation." (PMID 38652558, 2024). "However, the authors of this Mendelian randomisation also observed in the separate gout case-control data set that genetic variation in AHR, one of the strongest genetic effects on habitual coffee consumption, did not contribute to the protective effect for gout." (PMID 29976226, 2018).
hemangioma (2 papers, 2023 to 2024). A benign vascular lesion characterized by the formation of capillary-sized or cavernous vascular channels. "Furthermore, AhR knockout mice featured an increased tumor spectrum, with growth of hemangiomas, adenocarcinomas, suspected cutaneous neoplasia, and suspected carcinomas, while AhR wild-type mice did not develop these." (PMID 37106727, 2023).
Horizontal nystagmus (2 papers, 2013 to 2018). Nystagmus consisting of horizontal to-and-fro eye movements. "We have demonstrated that AhR deletion in mice leads to the occurrence of a spontaneous pendular horizontal nystagmus." (PMID 30149528, 2018). "The AhR is also expressed in the RGC of the mouse retina, and the dysregulation of such cells in AhR KO mice could be also a key event in the occurrence of the spontaneous pendular horizontal nystagmus." (PMID 30149528, 2018). "Here, we report that the constitutive absence of the AhR in adult mice (AhR−/−) leads to abnormal eye movements in the form of a spontaneous pendular horizontal nystagmus." (PMID 23301081, 2013).
Hyperinsulinemia (2 papers, 2023 to 2025). An increased concentration of insulin in the blood. "Both AhRKO and AhR+/− male mice were protected from hyperinsulinemia on HFD." (PMID 37443781, 2023). "Another AhR agonist, flutamide, a nonsteroidal antiandrogen, has been shown to reduce hyperinsulinemia." (PMID 41440753, 2025).
Hyperkeratosis (2 papers, 2022). Hyperkeratosis is a histopathological term defining a thickened stratum corneum and may be present in many different skin conditions, with many possible overlaps. "In one study, the dorsal skin of AhR-null mice showed hyperkeratosis, acanthosis, and marked dermal fibrosis, suggesting a role for AhR in controlling skin differentiation." (PMID 35625824, 2022). "The formation of AHR-RelA complexes may also help explain some of the adverse toxicological outcomes of AHR ligands such as immunosuppression, thymic involution, hyperkeratosis, and carcinogenesis." (PMID 35465323, 2022).
Impaired glucose tolerance (2 papers, 2015 to 2025). An abnormal resistance to glucose, i.e., a reduction in the ability to maintain glucose levels in the blood stream within normal limits following oral or intravenous administration of glucose. "To test whether the impaired glucose tolerance in AHR KO mice is caused by reduced insulin release we assessed the insulin secretory capacity of the animals." (PMID 26664351, 2015). "Preclinical data show impaired glucose tolerance, particularly in males and dependent on AhR, in response to CB77 during calorie restriction in mice but no impact on mass change." (PMID 39716022, 2025).
invasive breast carcinoma (2 papers, 2013 to 2017). A carcinoma that infiltrates the breast parenchyma. "In addition, a highly significant correlation between the AhR expression and invasive breast carcinoma was reported." (PMID 28103884, 2017).
juvenile idiopathic arthritis (2 papers, 2025). Juvenile idiopathic arthritis (JIA) is the term used to describe a group of inflammatory articular disorders of unknown cause that begin before the age of 16 and last over 6 weeks. "Finally, in patients with systemic juvenile idiopathic arthritis, low AhR activity in monocytes correlated with elevated cytokine responses." (PMID 41321306, 2025).
kidney cancer (2 papers, 2023 to 2024). Primary or metastatic malignant neoplasm involving the kidney. "Ligands of the AHR are in clinical development for the treatment of kidney cancer (ClinicalTrials.gov Identifier: NCT04069026)." (PMID 38319076, 2024). "This pan-genomic study of crosstalk between HIF and AHR transcription factors reveals both antagonistic and cooperative interactions and highlights their relevance to kidney cancer and its treatment." (PMID 36725335, 2023). "Therefore, therapies that block HIF-2 dimerization can release more HIF-1β/ARNT to bind with AHR, thereby potentially promoting the oncogenic effects of the AHR pathway in kidney cancer." (PMID 36725335, 2023). "To further evaluate the relevance of our findings to kidney cancer, we next examined the crosstalk between HIF and AHR in RNA-sequencing analyses of ccRCC tumours from The Cancer Genome Atlas (TCGA-KIRC) cohort." (PMID 36725335, 2023).
lymph node metastasis (2 papers, 2020 to 2023). "Since AHR, RhoA and ROCK1 were all associated with lymph node metastasis and clinical stage, and they correlated significantly with each other, we wondered if they had any relationships with overall survival time." (PMID 32546278, 2020). "UALCAN database analyses based on the THCA dataset indicated that patients with lymph node metastasis exhibited higher expressions of TET3 and AHR (P < 0.001)." (PMID 37718440, 2023).
Merkel cell carcinoma (2 papers, 2019 to 2021). "Increased activity of the AHR- IDO1-TDO2 pathway in the tumor microenvironment is related to poor prognosis in Merkel cell carcinoma, which is consistent with the results of the present study." (PMID 34784845, 2021).
myeloid leukemia (2 papers, 2022 to 2024). A clonal proliferation of myeloid cells and their precursors in the bone marrow, peripheral blood, and spleen. "Interestingly, the role of AHR in myeloid leukemia is quite the opposite." (PMID 39125717, 2024).
myeloproliferative disorder (2 papers, 2015 to 2016). A clonal hematopoietic stem cell disorder, characterized by proliferation in the bone marrow of one or more of the myeloid (i.e., granulocytic, erythroid, megakaryocytic, and mast cell) lineages. "AHR mice have shown signs of early aging and myeloproliferative disease." (PMID 27366154, 2016). "Earlier reports from AHR-KO mice indicated changes in multiple signaling pathways that promote premature HSC exhaustion and development of myeloproliferative disorder." (PMID 27366154, 2016). "Lack of aryl hydrocarbon receptor (AhR) has been associated with alterations in gene expression related to HSC function and the subsequent development of a myeloproliferative disorder in aging female mice." (PMID 26208102, 2015).
ovarian dysfunction (2 papers, 2016 to 2019). The inability of the ovaries to function. "Activated AHR can cause ovarian dysfunction in females and decrease and degeneration of sperm cells in males." (PMID 31861561, 2019). "Besides, it has been shown in mouse that PAHs exposure promoted ovarian failure through AhR-mediated bax activation." (PMID 29051429, 2016).
ovarian tumor (2 papers, 2020 to 2024). "In addition to CYP1A1 induction and AhR nuclear translocation, other markers of sensitivity to 5F 203 have been identified in ovarian tumors." (PMID 32443455, 2020).
paracoccidioidomycosis (2 papers, 2019 to 2020). A systemic fungal infection caused by Paracoccidioides brasiliensis that is most often seen in immunocompromised patients. "Because of its important role at epithelial barriers, we evaluate the role of AhR in the outcome of a pulmonary model of paracoccidioidomycosis." (PMID 32647342, 2020). "Collectively our data demonstrate that in pulmonary paracoccidioidomycosis AhR controls fungal burden and excessive tissue inflammation and is a possible target for antifungal therapy." (PMID 32647342, 2020).
Peri-Implantitis (2 papers, 2022 to 2024). An inflammatory process with loss of supporting bone in the tissues surrounding functioning DENTAL IMPLANTS. "A case-control study involving the collection of tissue biopsies from volunteers diagnosed with peri-implantitis and healthy controls revealed elevated levels of gene expression of AhR and IL-6 in peri-implantitis tissues." (PMID 39575260, 2024). "In conclusion, higher gene expression levels for AhR and IL-6 were detected in the soft tissues of peri-implantitis patients." (PMID 35742682, 2022). "The present case-control study evaluated the gene expression of AhR, IL-22, and IL-6 in the peri-implant tissues of healthy and peri-implantitis patients." (PMID 35742682, 2022). "Since peri-implantitis is an inflammatory disease initiated by bacteria, the changes in AhR expression and its activation may be directly related to the dysbiosis condition." (PMID 35742682, 2022). "Higher levels of gene expression of AhR and IL-6 were detected in peri-implantitis tissues." (PMID 35742682, 2022).
perinatal asphyxia (2 papers, 2020 to 2025). A disorder caused by a lack of blood flow or gas exchange to or from the fetus in the period immediately before, during, or after the birth process. "Like its precursor, DIM downregulated HIF-1α in perinatal asphyxia and inactivated the AHR/NMDA signaling and hypermethylation of specific genes (AHR and GRIN2b)." (PMID 40094833, 2025).
peritonitis (2 papers, 2018 to 2022). Inflammation of the peritoneum (tissue that lines the abdominal wall and covers most of the organs in the abdomen). "Adoptive transfer of AhR-expressing macrophages protected mice against LPS-induced peritonitis associated with high IL-10 production." (PMID 30283437, 2018). "The significance of IL-10 and IL-22 upon AhR activation for preventing septic course of S.E.-induced peritonitis has to be elucidated in further studies." (PMID 35203386, 2022). "In summary, the results of this study show that AhR activation through BaP exerts a significant impact on the course and outcome of septic peritonitis, and thus, highlight the key role of this receptor in immune cells." (PMID 35203386, 2022). "Intriguingly, we found that adoptive transfer of AhR-expressing PMs protected mice against LPS-induced peritonitis via increased IL-10-production." (PMID 30283437, 2018). "Furthermore, compared with PBS or Ad-NC, Ad-AhR significantly improved the survival of mice in the lethal LPS-induced peritonitis model." (PMID 30283437, 2018).
primary biliary cholangitis (2 papers, 2021). Primary biliary cholangitis (PBC) is a chronic and slowly progressive cholestatic liver disease of autoimmune etiology characterized by injury of the intrahepatic bile ducts that may eventually lead to liver failure. "Regarding primary biliary cholangitis (PBC), there is emerging evidence that AHR might be involved in dysregulation of T cell responses." (PMID 34075438, 2021).
Pruritus (2 papers, 2020 to 2023). Pruritus is an itch or a sensation that makes a person want to scratch. "Those AhR-CA mice overexpress Artn, which, as a target gene of AhR, can induce substantial pruritus during the chronic presence of PAHs, as evaluated by continuous scratching behavior." (PMID 37445680, 2023).